KDM6A (lysine demethylase 6A)
Diseases named in the same sentence as KDM6A in open-access papers (continued):
Sharing a sentence is not in itself a finding about the gene and the disease.
tumor (continued). "Most of the variations of KDM6A in PDAs are loss of copy number with a few cases of single nucleotide variation, in-frame deletion, or amplification, suggesting a potential tumor suppressive role in PDA." (PMID 27999365, 2016). "Despite infrequent inactivation in many cancers, mutation and functional data have established that KDM6A is a bona fide tumor suppressor gene." (PMID 24622842, 2014). "Among the first cancer-associated mutations in KDMs that were identified were those in KDM6A following sequencing of 1,390 patient tumor samples." (PMID 24622842, 2014). "One can surmise that in an elderly patient with an already waning immune system, the loss of KDM6A could be a double blow–epigenetically silencing immune-response genes in the tumor and thus further reducing immune cell recruitment to the tumor site." (PMID 40918525, 2025). "KDM6A lies somewhere in between, whereby around 10% of KDM6A mutations in tumours could be explained as passenger events, suggesting a weaker driver potency." (PMID 39920335, 2025). "Furthermore, the loss of function of epigenetic regulators, such as KDM6A, can induce secondary demethylation changes that contribute to tumour progression." (PMID 40806634, 2025). "Functional studies illustrate that loss of KDM6A or KMT2D promotes tumor growth and may sensitize cells to specific targeted therapies such as EZH2 inhibitors." (PMID 41373802, 2025). "Sex hormones and X-linked genes (e.g., higher KDM6A in females) modulate tumor biology." (PMID 41346390, 2025). "Additionally, the loss of KDM6A‐mut creates an epigenetic state that drives tumor growth and is crucial for pathogenesis and treatment." (PMID 40693457, 2025). "KDM6A mutations may enhance tumor cell drug resistance or promote immune evasion, thereby affecting treatment outcomes and recurrence rates." (PMID 40647534, 2025). "Genetic analysis of the tumor tissue post-surgery revealed a KDM6A gene mutation." (PMID 40297816, 2025). "Together, the EZH2 and KDM6A reports raise the possibility that H3K27 demethylation may underlie a female-biased tumor suppressor phenotype, while EZH2 and PRC2 activity may underlie a male-biased oncogenic phenotype." (PMID 38949020, 2024). "Evidence indicates that the loss of function of KDM6A could increase the H3K27me3 level at the promoter region of multiple tumor suppressor genes, subsequently promoting tumor malignancy." (PMID 38850159, 2024). "KDM6A is a tumour suppressor gene that is often mutated in BCa." (PMID 38338835, 2024). "Furthermore, we used IHC and Oil Red ‘O’ staining to evaluate the level of lipid metabolism and we found that Kdm6a‐deficient tumour tissues exhibited a lower staining intensity than the WT tissues." (PMID 37846441, 2023). "Then, if KDM6A acquires a mutation before or after tumor development, it could possibly drive higher-grade tumors in patients with female chromosomal sex." (PMID 37666817, 2023). "Moreover, it has been observed that Kdm6a loss accelerates tumor progression and metastasis development in genetically engineered PDAC mouse models, particularly in a gender-specific fashion." (PMID 37659057, 2023). "The most frequently mutated factors include the H3K4 mono-methyltransferases MLL3 and MLL4 (encoded by the genes KMT2C and KMT2D, respectively) and their cofactor, the H3K27 demethylase UTX (KDM6A); the prevalence of mutations affecting these factors indicates their broad roles as tumor suppressors." (PMID 37252797, 2023). "Patients with KDM6A-deficient tumours could benefit of targeted therapy focusing on mTORC1 inhibition." (PMID 34509979, 2022). "Although KDM6A undoubtedly controls other cancer relevant genes and pathways beyond mTORC1, our data reveal that KDM6A-deficient tumours are sensitive to mTORC1 inhibition and suggest that KDM6A could serve as a biomarker for therapies focussing on mTORC1." (PMID 34509979, 2022).
tumor (continued). "Importantly, KDM6A expression in human tumours correlates with mTORC1 activity and KDM6A-deficient tumours exhibit increased sensitivity to mTORC1 inhibition." (PMID 34509979, 2022). "The integrated multi‐omics analysis revealed that despite the heterogeneities observed in certain omics, low expression of ZNF521 and loss of KDM6A copy number were consistently presented within and across individual tumours, serving as potential biomarkers for PDAC." (PMID 35061935, 2022). "In addition, KDM6A mutation was associated with a lower number of tumour-infiltrating immune cells (TIICs) and indicated a state of immune tolerance." (PMID 34051747, 2021). "Other groups have identified inactivating KDM6A mutations in a wide variety of tumor types." (PMID 34780480, 2021). "Scanning cancer mutations in various tumor types for genes exhibiting more mutations in men than in women led to the characterization of six genes implicated as tumor suppressors, all on the X chromosome, including KDM6A." (PMID 33498655, 2021). "Overall, we conclude that KDM6A mutation is frequent in BC and promotes tumour immune escape, which may serve as a novel biomarker to predict the immune response." (PMID 34051747, 2021). "Several recent studies identified inactivating mutations of KDM6A in different cancer tissues, along with decreased expression levels of KDM6A in cancer compared with those in normal tissues, further supporting that KDM6A is a tumour suppressor." (PMID 34051747, 2021). "Lysine-specific demethylase 6A (KDM6A) is frequently mutated in several cancer types; however, its effects on tumour progression and clinical outcome in BC remain unclear." (PMID 34051747, 2021). "KRAS and KDM6A mutations were detected in tumor samples collected from each patient." (PMID 32466769, 2020). "It will also be critical to exclude the possibility that loss of KDM6A in the male germ line leads to increased DNA damage and accumulation of genomic mutations that could contribute to a tumor phenotype in the next generation." (PMID 30963999, 2019). "We then turned our attention to the molecular mechanism by which loss of Kdm6a in the germ line might affect tumor susceptibility in the next generation." (PMID 30963999, 2019). "However, a subsequent study showed that KDM6B is required for the initiation and maintenance of T-ALL, while KDM6A acts as a tumor suppressor in T-ALL and is frequently mutated in this cancer." (PMID 28717873, 2018). "Finally, we characterize a putative actionable epigenetic switch involving HOX-genes with strong correlations to tumor differentiation states and propose that a link exits between KDM6A mutations and HOXA9 gene expression patterns." (PMID 25810763, 2015). "KDM6A catalyzes the demethylation of tri/di methylated histone H3 at lysine 27 which is associated with transcriptional activation hence this enzyme has global effects to activate either tumor growth or suppression." (PMID 26556859, 2015). "Finally, the basal-like subgroup was also enriched for mutations in the H3K27 demethylase KDM6A, which is highly indicative of the key role of chromatin remodeling genes in establishing tumor aggressiveness in this subgroup." (PMID 26431491, 2015). "Furthermore, tumours with low KDM6A levels were typically associated with high pS6RP levels." (PMID 34509979, 2022). "In this regard, we now propose that stochastic dynamics of epigenetic switching suffices to dictate the emergence (and persistence) of tumor cell sub-populations with distinct degrees of responsiveness to EZH2 inhibitors in the absence of inactivating mutations of the EZH2 epigenetic partner KDM6A." (PMID 34153035, 2021). "In addition, inactivating mutations in tumor suppressor genes such as lysine demethylase 6A (KDM6A), cAMP-response element binding protein (CREBBP), and excision repair cross-complementation 2 (ERCC2) among other genes are important in the establishment and growth of NMIBC tumors." (PMID 31137849, 2019).
tumor (continued). "Loss of KDM6A activity may sensitize tumor cells to demethylating agents such as EZH2 inhibitors." (PMID 29989027, 2018). "It is important to note that a particular subclone with the set of gene mutations (e.g. STEAP3, SLURP1 and KDM6A) within the primary tumor may have grown out or outcompeted the others and survived both chemotherapy selection and allo-HSCT treatment to evolve into the dominant clone at relapse." (PMID 26527318, 2016). "Knockdown of TNKS and KDM6A sensitized CisR A549, H1299, and H358 tumor spheroids to cisplatin, resulting in reduced cell viability and increased levels of cleaved caspase-7." (PMID 40860181, 2025). "These loss-of-function mutations have significant epigenetic consequences: KDM6A normally removes repressive H3K27 methylation marks, so its loss can lead to an increase in the repressive H3K27me3 mark on tumor suppressor gene promoters." (PMID 40918525, 2025). "Similar sex-biased expression patterns are observed in other malignancies like clear cell renal carcinoma, suggesting tissue-specific tumor suppressor functions of KDM6A." (PMID 41019050, 2025). "While our findings support a tumor‐suppressive role for KDM6A in HCC, it is essential to consider potential challenges associated with therapeutic modulation of this epigenetic regulator in vivo." (PMID 41244070, 2025). "In contrast, the inactivation of KDM6A induced colorectal cancer cell survival in vitro and tumor growth in vivo." (PMID 40940894, 2025). "Low expression of KDM6A leads to accelerated tumor growth in males with potentially greater therapeutic benefit from anti-PD-1 treatment, while maintaining superior functional capacity to constrain tumor progression in females." (PMID 41019050, 2025). "The elevated mutation rate in KDM6A among women is of particular interest given its location on the X chromosome and its role in providing a “two-hit” vulnerability due to incomplete X-inactivation and may partly explain sex-based differences in tumor biology and outcomes." (PMID 41373802, 2025). "X-linked tumor suppressor genes further modulate these disparities, particularly KDM6A, which escapes X-inactivation and is expressed at higher levels in female cells, enhancing tumor suppression." (PMID 41346390, 2025). "To understand the contribution of KDM6A demethylase activity in tumor growth, we performed colony formation assays reintroducing KDM6A WT and the dead mutant in KDM6A KO." (PMID 41085408, 2025). "Previous research has primarily focused on the impact of the KDM6A expression level on tumor recurrence and treatment resistance, with limited direct data on complete remission rates." (PMID 40647534, 2025). "The role of KDM6A in cancer development is cell-context specific, acting either as a tumor suppressor or as an oncogenic factor." (PMID 41085408, 2025). "While immune inhibitory genes are often upregulated in tumors to suppress anti-tumor immunity, their concurrent downregulation with KDM6A and FN1 suggests an alternative mechanism of immune escape, possibly creating a less immunogenic microenvironment." (PMID 39833941, 2025). "Lysine-specific demethylase 6 A (KDM6A/UTX), a frequently mutated tumor suppressor and H3K27me2/3 demethylase in PC, influences PDAC cell identity, tumor sphere formation, migration, and invasion across multiple cell lines." (PMID 40619414, 2025). "The expression of the KDM6A protein in PDAC tumour tissue has been investigated by several groups, all observing reduced expression of the tumour suppressor in a large proportion of patients’ tumours." (PMID 40723241, 2025). "In parallel, frequent mutations in chromatin modifiers (e.g., KDM6A, KMT2D) and overexpression of histone-modifying enzymes (e.g., EZH2) alter the tumor epigenome to promote immune evasion and tumor aggressiveness." (PMID 40918525, 2025).
tumor (continued). "Consistent with the changes in protein levels, TNKS and KDM6A mRNA levels were reduced in all CisR tumor spheroids following CREB knockdown combined with cisplatin treatment." (PMID 40860181, 2025). "Our method can not only uncover disease-causing genes with abnormal expression in tumor samples such as CD74, HGF, but it can also identify genes with stable expression yet crucial roles in LUSC, such as BRAF, KDM6A, MAP2K1, and TPR." (PMID 40136480, 2025). "The panel NGS of the primary tumor revealed pathogenic mutations in VHL, BAP1 and NF2 and likely pathogenic mutations in KDM6A, as well as ABL." (PMID 38611655, 2024). "In summary, the heightened expression of KDM6A in female tissues is crucial for maintaining cellular homeostasis, plays a key role in X chromosome-mediated tumor suppression, and offers greater protection against specific cancers in females." (PMID 39731171, 2024). "KDM6A gene is also a tumor suppressor gene and a member of the histone H3 lysine 27 demethylase gene family." (PMID 39118085, 2024). "Numerous studies proved compelling evidence indicating that KDM6A in tumor cells not only contributes to tumorigenesis but also increases resistance to chemotherapy, such as imatinib treatment for chronic myelogenous leukemia (CML)." (PMID 38850159, 2024). "We validated KDM6A/KDM6B as the target of GSK-J4 since KDM6A/KDM6B genetic depletion had a similar effect to GSK-J4 on cisplatin-mediated anti-tumor activity and transcriptome alterations." (PMID 39482699, 2024). "Significant correlations were observed between the transcript levels of MB21D1 (cGAS), TMEM173 (STING), and KDM6A (UTX) in the scRNA‐seq data of mice tumor infiltrating NK cells." (PMID 39206412, 2024). "Similar to GSK-J4, KDM6A/ KDM6B-knockdown minimally effected basal tumor growth but dramatically potentiated the effects of cisplatin, again with evidence of tumor regression, and all mice remained tumor-free for over 90 days after a single dose of cisplatin." (PMID 39482699, 2024). "We validated KDM6A/KDM6B as the target of GSK-J4 since KDM6A/KDM6B genetic depletion had a remarkably similar effect to GSK-J4 on cisplatin-mediated anti-tumor activity and transcriptome alterations." (PMID 39482699, 2024). "Ubiquitously transcribed tetratricopeptide repeat on chromosome X (UTX), also known as lysine (K)-specific demethylase 6A (KDM6A), functions as a tumor suppressor gene or oncogene depending on the tumor type and context." (PMID 37692474, 2024). "Taken together, these results show that indirect inhibition of MMP3 via targeting KDM6A prevents metastasis of KMT2C or KMT2D mutant tumours." (PMID 38926506, 2024). "This insight reinforces the potential of HDAC inhibitors as targeted therapies for KDM6A-deficient PDAC cells, aiming to restore the expression of crucial tumor suppressors and counteract PDAC progression." (PMID 38791111, 2024). "The gene UTX (also known as KDM6A) encodes a histone H3K27 demethylase and is a tumor suppressor frequently altered in human cancers." (PMID 38827026, 2024). "In a mouse model, treatment with a CXCL1-neutralizing antibody blocked the chemotactic and NET-promoting properties of KDM6A-deficient PDAC cells and suppressed tumor growth, highlighting its potential as a targeted treatment strategy." (PMID 38791111, 2024). "Rui Yang and his team demonstrated that the transcription factor homeobox A3 (HOXA3) promotes aerobic glycolysis in GBM cells by activating the transcription of lysine-specific demethylase KDM6A, thereby promoting tumor growth." (PMID 39493751, 2024). "UTX (KDM6A), MLL3 (KMT2C), and MLL4 (KMT2D), the core catalytic components of the COMPASS-like complex, are all considered tumor suppressors, with frequent loss-of-function genomic alterations found in a broad spectrum of human cancers." (PMID 37261974, 2023). "KDM6A is important for the differentiation of embryonic stem cells and the development of various tissues and functions as a tumor suppressor." (PMID 38138214, 2023).
tumor (continued). "On the other hand, other studies have shown that KDM6A deficiency results in a faster tumour cell growth, suggesting that KDM6A is a tumour suppressor." (PMID 37846441, 2023). "Diethylnitrosamine (DEN)‐CCL4 mouse liver tumour and the xenograft tumour models were used to evaluate the function of KDM6A in HCC progression." (PMID 37846441, 2023). "From a tumor cell-intrinsic perspective, KDM6A is involved in regulating the mTORC1 signaling pathway in liver cancers and PDACs, presenting opportunities for the precise use of mTOR inhibitors." (PMID 37659057, 2023). "In support for the present work, several previous studies have reported that KDM6A plays an oncogenic role in tumour progression." (PMID 37846441, 2023). "In both normal and tumor cells, certain genes, such as KDM6A, escape the X-chromosome inactivation process and become expressed at significantly higher levels in individuals of female chromosomal sex compared to male chromosomal sex." (PMID 37666817, 2023). "As expected, the IHC scores of Fgfr3 and Fgfr4 were decreased in Kdm6a‐deficient tumour tissues, confirming that FGFR3 and FGFR4 expression was positively associated with KDM6A expression." (PMID 37846441, 2023). "To decipher the role of KDM6A in normal versus tumor settings, we identified the genomic landscape of KDM6A in normal, immortalized, and cancerous bladder cells." (PMID 36980177, 2023). "To further investigate the role of KDM6A in lenvatinib sensitivity, we performed an in vivo tumour graft experiment by injecting Kdm6a knockdown (or SCR) Hepa1–6 cells then administered with lenvatinib." (PMID 37846441, 2023). "Using primary cell lines derived from tumours before Dox switch (Myc;TREshKdm6a cells), we observed potent Kdm6a induction on mRNA and protein levels on Dox withdrawal." (PMID 34509979, 2022). "Collectively, these data show that KDM6A expression correlates with DEPTOR expression in human tumours and is accompanied with activation of mTORC1." (PMID 34509979, 2022). "In contrast to KDM6B, which seems to activate oncogenic gene expression to support AML pathogenesis, KDM6A has recently been shown to play a tumour suppressor role in AML." (PMID 35915507, 2022). "In various types of malignancies, KDM6A predominantly serves a tumour suppressor role, whereas KDM6B functions as an oncogenic protein." (PMID 35915507, 2022). "Collectively, these experiments demonstrate that sustained Kdm6a suppression protects from apoptosis and is required for tumour maintenance in vivo and in vitro." (PMID 34509979, 2022). "By classifying tumours in low and high expression levels of individual proteins, we found a significant correlation of low KDM6A expression with low DEPTOR expression and vice versa." (PMID 34509979, 2022). "Many studies had demonstrated the function of KDM6A in differentiation, development, regeneration, and tumor suppression." (PMID 36277066, 2022). "Further, we generated primary cell lines of these tumours and performed similar Kdm6a re-expression experiments as conducted before in liver cell lines." (PMID 34509979, 2022). "Recently, the histone demethylase KDM6A tumor suppressor capacity has been shown to be dependent on the ability of its IDR to phase separate." (PMID 35887017, 2022).